FBN2 (fibrillin 2)
Diseases named in the same sentence as FBN2 in open-access papers (continued):
Sharing a sentence is not in itself a finding about the gene and the disease.
lung carcinoma (4 papers, 2022 to 2024). "Similar to this, elevated FBN2 expression was discovered to be a risk factor for stomach and lung cancer." (PMID 37337404, 2023). "FBN2 is highly expressed in lung cancer tissues, and as an oncogene, it affects the pathogenesis of lung cancer." (PMID 35299749, 2022). "Mutation of CSMD3 in non‐small‐cell lung cancer leads to increased proliferation of airway epithelial cells, and abnormal methylation of FBN2 is a biomarker for lung cancer." (PMID 34951053, 2022).
metastatic tumors (4 papers, 2017 to 2022). "Since the expression levels of CTHRC1, FBN2, NTM, PDGFC, PDLIM3, and SLC16A3 are significantly differentiated among the normal samples, primary tumor, and metastatic tumor, we anticipated that these genes are associated with metastasis in colon cancer." (PMID 35991839, 2022). "Moreover, the CTHRC1, PDGFC, PDLIM3, NTM, and SLC16A3 genes are gradually increased from normal tissue to the tumor and tumor to the metastatic tumor, and FBN2 showed the reverse pattern." (PMID 35991839, 2022). "Besides, the expression of FBN2 is gradually downregulated from normal to the metastatic tumor, indicating that the downregulation of this gene is associated with tumor progression (Welch’s t-test, p < 0.05)." (PMID 35991839, 2022).
age-related macular degeneration (3 papers, 2019 to 2023). Age-related loss of vision in the central portion of the retina (macula), secondary to retinal degeneration. "Rare dominant variants in FBN2 have been described in relationship with early onset macular degeneration (OMIM 616118) but also age-related macular degeneration." (PMID 34148116, 2022). "Mutations in the extracellular matrix gene Fibrillin-2 (FBN2) are related to genetic macular degenerative disorders including age-related macular degeneration (AMD) and early-onset macular degeneration (EOMD)." (PMID 37100863, 2023).
colon cancer (3 papers, 2022 to 2023). "Since the upregulated group of CTHRC1, NTM, PDGFC, PDLIM3, and SLC16A3 and the downregulated group of FBN2 genes are consistently correlated with the shorter survival time in TCGA and GEO datasets, we investigated the association of these genes with immune score and stromal scores in colon cancer." (PMID 35991839, 2022). "Currently, more in‐depth research has been done on the involvement of FBN2 primarily in colon cancer." (PMID 37337404, 2023). "The upregulation of CTHRC1, PDGFC, PDLIM3, NTM, and SLC16A3 and downregulation of FBN2 are correlated with a shorter survival time in colon cancer." (PMID 35991839, 2022). "In summary, these results indicated that the expression of CTHRC1, FBN2, NTM, PDGFC, and PDLIM3 is associated with tumor progression and metastasis of colon cancer cells." (PMID 35991839, 2022). "In our research, we found that FBN2 is highly expressed in normal fibroblasts, and downregulated FBN2 is consistently correlated with the shorter survival of colon cancer patients, this result gives rise to the idea to study the role of FBN2 in a deeper way." (PMID 35991839, 2022). "This indicated that the expression levels of CTHRC1, FBN2, NTM, PDGFC, and PDLIM3 genes are associated with the modulation of immune and stromal activity in the colon cancer tumor microenvironment." (PMID 35991839, 2022). "Although little is known about FBN2 biological function regarding epigenetic changes in human cancers, the methylation of these genes has great potential to detect early-stage colon cancer." (PMID 35991839, 2022). "Finally, we validated the expression levels of these key genes in the colon tumor stroma dataset, and we revealed that the CTHRC1, NTM, PDGFC, and FBN2 genes are consistently altered in colon tumor stroma." (PMID 35991839, 2022). "In addition, downregulated FBN2 is consistently downregulated in colon tumor stroma." (PMID 35991839, 2022). "In contrast, the downregulated group of FBN2 gene is consistently correlated with the shorter survival of colon cancer patients in GSE17536, indicating the tumor-suppressive role of FBN2 in colon cancer." (PMID 35991839, 2022). "The FBN2 gene is hypermethylated in CRC tissue and serum samples from patients with CRC and liver metastases, and its expression is directly correlated with shorter survival rates in colon cancer patients, suggesting a possible role as a tumor suppressor gene." (PMID 37214090, 2023). "Interestingly, we found that the expression levels of CTHRC1, FBN2, NTM, PDGFC, and PDLIM3 are positively correlated with the ssGSEA scores of metastatic-promoting genes in colon cancer (Spearman’s correlation test, p < 0.001)." (PMID 35991839, 2022). "Finally, we investigated the correlation of CTHRC1, FBN2, NTM, PDGFC, PDLIM3, and SLC16A3 with the metastatic scores in colon cancer data." (PMID 35991839, 2022). "Furthermore, the CTHRC1, FBN2, PDGFC, PDLIM3, and NTM genes are positively correlated with the metastatic scores in colon cancer." (PMID 35991839, 2022). "However, the expression levels of PDLIM3 and SLC16A3 are not significantly altered in colon tumor stroma (p < 0.05) and the expression level of FBN2 showed the opposite trend in the high-CAFs group." (PMID 35991839, 2022).
lung adenocarcinoma (3 papers, 2014 to 2024). A carcinoma that arises from the lung and is characterized by the presence of malignant glandular epithelial cells. "FBN2 disruption precedes the subclonal deletion of genes along chromosome 9p, including significantly mutated known lung adenocarcinoma genes SMARCA4, KEAP1, and STK11." (PMID 25160065, 2014).
mesothelioma (3 papers, 2017 to 2019). A usually malignant and aggressive neoplasm of the mesothelium which is often associated with exposure to asbestos. "We have previously shown high expression of FBN1 and FBN2 as well as MMP2 in association with high GREM1 expression in JP5 cells as well as in other mesothelioma cells." (PMID 29968778, 2018). "Fibrillin-2 is upregulated in mesothelioma and localises gremlin-1 to the tumour microenvironment where it binds fibrillin-1 and -2 and colocalises with microfibrils in cells and mesothelioma tumours." (PMID 30016650, 2019). "Our previous studies suggest that mesothelioma cells secrete high amounts of gremlin-1, which is targeted into fibrillin-2 rich microfibrils in the mesothelioma tumor tissue." (PMID 29228689, 2017).
non-small cell lung carcinoma (3 papers, 2020 to 2022). A group of at least three distinct histological types of lung cancer, including non-small cell squamous cell carcinoma, adenocarcinoma, and large cell carcinoma. "Methylation inactivation of FBN2 was associated with invasion and metastasis of non-small cell lung cancer, but loss of this gene might be involved in pathogenesis of pituitary prolactinoma." (PMID 33709028, 2021).
rhabdomyosarcoma (3 papers, 2020 to 2023). A rare aggressive malignant mesenchymal neoplasm arising from skeletal muscle. "It has been reported that FBN2 could have excellent diagnostic value for smooth muscle sarcoma and rhabdomyosarcoma." (PMID 35991839, 2022). "FBN2 has been identified as a diagnostic biomarker in leiomyosarcoma and rhabdomyosarcoma." (PMID 32084007, 2020). "Additionally, it has been suggested that FBN2 may be a highly effective diagnostic tool for rhabdomyosarcoma and smooth muscle sarcoma." (PMID 37337404, 2023).
tendinopathy (3 papers, 2016 to 2024). "We investigated the potential influence of single nucleotide polymorphisms (SNPs) in fibrillin-2 (FBN2), tenascin-C (TNC), and matrix metalloproteinase-3 (MMP3) on the tendon regeneration failure phenotype and impact on the susceptibility to tendinopathy in Brazilian high-performance athletes." (PMID 39594135, 2024). "The FBN2 (rs331079), TNC (rs2104772), and MMP3 (rs591058) SNPs were in Hardy–Weinberg equilibrium in the overall participants athletes and in each group (tendinopathy cases and controls)." (PMID 39594135, 2024). "Given these implications, FBN2 (rs331079), TNC (rs2104772), and MMP3 (rs591058) SNPs may contribute to a more susceptible ECM tendon regeneration failure phenotype, and their interaction with environmental determinants may influence the individual risk for tendinopathy." (PMID 39594135, 2024).
asthma (2 papers, 2015 to 2024). "Quantitative PCR was used to monitor the impact of storage conditions on the expression of housekeeping genes: GAPDH and β-actin, and the asthma related genes: POSTN and FBN2." (PMID 38948078, 2024).
bladder cancer (2 papers, 2023 to 2025). "We conducted an in‐depth study on the prognostic properties of FBN2 in BLCA and its influence on immune and chemotherapy drugs in order to gain a comprehensive understanding of the role of FBN2 in bladder cancer." (PMID 37337404, 2023).
cerebrovascular disease (2 papers, 2014 to 2025). "Notably, although cardiovascular involvement is uncommon in CCA, recent case reports suggest an association between FBN2 mutations and intracranial aneurysms, highlighting the gene’s potential role in cerebrovascular disease." (PMID 41146935, 2025).
gastric cancer (2 papers, 2021 to 2022). A primary or metastatic malignant neoplasm involving the stomach. "In contrast, high expression of FBN2 was found as a risk factor in lung and gastric cancer." (PMID 35991839, 2022).
glioma (2 papers, 2023 to 2024). A benign or malignant brain and spinal cord tumor that arises from glial cells (astrocytes, oligodendrocytes, ependymal cells). "For the sake of clarifying the expression of BMGs in glioma, this study screened 9 BMGs that were upregulated in glioma (FBN2, FREM3, Lamb4, MEP1A, MMP1, MMP7, OPTC, EVA1A, and ADAMTS20) from TCGA -GTEX expression matrix." (PMID 37335645, 2023).
Hypertension (2 papers, 2024). The presence of chronic increased pressure in the systemic arterial system. "This study identified novel loci associated with hypertension, including FBN2 and JPH2." (PMID 39011893, 2024). "Concentrating specifically on SNPs rs17677724 and rs1014754, the effect allele ’T’ linked to reduced FBN2 expression in the heart-left ventricle (β = −0.684, SE = 0.109, P value = 3.42 × 10−9), exhibited a significant, positive association with hypertension (β = 0.492, P value = 7.4 × 10−9)." (PMID 39011893, 2024). "Mendelian randomization utilizing two identified variants (rs17677724 and rs1014754) suggested that a genetically induced decrease in heart FBN2 expression and an increase in adrenal gland JPH2 expression were causally linked to hypertension." (PMID 39011893, 2024). "Previous studies supporting the correlation of FBN2 with BP traits, particularly in heart tissue, underscore its role in shaping the passive mechanical properties of major arteries, contributing to early-onset hypertension." (PMID 39011893, 2024).
KBG syndrome (2 papers, 2022). KBG syndrome is a rare condition characterized by a typical facial dysmorphism, macrodontia of the upper central incisors, skeletal (mainly costovertebral) anomalies and developmental delay. "Furthermore, we found a double disease-causing heterozygous variant of FBN2 and ANKRD11 in a patient with blended phenotypes consisting of CCA and KBG syndrome." (PMID 35360850, 2022).
myopia (2 papers, 2023). "In contrast, selection favoring the risk allele associated with myopia predisposition was only observed in TSPAN10 and FBN2 (P = 8.63 × 10−11 for rs6860901)." (PMID 37919796, 2023). "We examined the top 64 myopia-associated loci that were expressed in the retinal layers and associated with common refractive errors, SNPs representing TSPAN10, KCNJ5, TFAP2B, and FBN2 had |nSL|> 2, which were under strong selection." (PMID 37919796, 2023).
osteoporosis (2 papers, 2019 to 2020). A condition of reduced bone mass, with decreased cortical thickness and a decrease in the number and size of the trabeculae of cancellous bone (but normal chemical composition), resulting in increased fracture incidence. "A number of the genes highlighted in this study present strongly as having a potential role in bone biology, including CPE, FBN2, FLCN and RIPK3, and our results support the growing body of evidence suggesting that the CPE gene may exert pleiotropic effects on type 2 diabetes and osteoporosis." (PMID 32216834, 2020).
sarcoma (2 papers, 2019 to 2024). A usually aggressive malignant neoplasm of the soft tissue or bone. "In terms of gene signatures, an immune-related five-gene signature based on MYBL2, FBN2, TSPAN7, GCSH, and DDX39B is a prognostic biomarker for sarcoma patients." (PMID 38240704, 2024).
Stillbirth (2 papers, 2023 to 2025). Death of the fetus in utero after at least 22 weeks of gestation. "al. identified inherited compound heterozygous variants of FBN2 in embryonic loss, our SV analysis in stillbirth in Family 4 confirmed a de novo SV (chr5:128335405) impacting FBN2, suggesting variants disrupting the FBN2 gene may be incompatible with development to the fetal stage." (PMID 36800380, 2023). "A study on exome sequencing found that missense mutations of COL2A1, PEIZO1, and HNF1B were associated with stillbirth, and ultra-rare variants in PTPN11, SMC3, and FBN2 were known to cause stillbirth." (PMID 39906474, 2025).
Stroke (2 papers, 2014 to 2023). Sudden impairment of blood flow to a part of the brain due to occlusion or rupture of an artery to the brain. "With regard to DMR findings, out of 149 DMRs identified, 2 DMRs were located in genes previously associated with stroke in a multi-ancestry GWAS: FBN2 and PDE3A genes." (PMID 37370144, 2023).
systemic lupus erythematosus (2 papers, 2020 to 2023). An autoimmune multi-organ disease typically associated with vasculopathy and autoantibody production. "The result of the GSEA based on KEGG enrichment suggested that the functions of DEGs in high FBN2 expression were enriched in systemic lupus erythematosus, neuroactive ligand receptor interaction, and olfactory transduction." (PMID 37337404, 2023).
systemic sclerosis (2 papers, 2020 to 2024). A chronic disorder, possibly autoimmune, marked by excessive production of collagen which results in hardening and thickening of body tissues. "FBN2 is involved in elastic fiber formation and is abundantly present in embryonic tissues, but is also elevated along with elastin in fibrotic tissue, for instance in systemic sclerosis." (PMID 33658982, 2020).
actinic keratosis (1 paper, 2023). A precancerous lesion of the skin composed of atypical keratinocytes. "Five new genes, HEPHL1, FBN2, SULF1, SULF2, and TCN1, were recently discovered in cSCC, which were significantly upregulated compared to normal skin (p < 0.001) and actinic keratosis (AK) (p < 0.01)." (PMID 36980718, 2023).
Arrhythmia (1 paper, 2024). Any cardiac rhythm other than the normal sinus rhythm. "It is noteworthy that the FBN2 gene was mutated in 13 patients; however, in 12 of them, mutations coexisted with other genes associated with MCP, arrhythmias, and FHC." (PMID 37688493, 2024).
autism spectrum disorder (1 paper, 2025). A spectrum of developmental disorders that includes autism, and Asperger syndrome. "In this study, through the analysis of CHD8A and CHD8B allelic deletion samples, we identified seven hub genes associated with Autism Spectrum Disorder (ASD): IGF2, FN1, CXCR4, COL11A1, ITGA6, LOX, and FBN2." (PMID 40526590, 2025).
brachydactyly (1 paper, 2017). A disease characterized by the presence of brachydactyly, including syndromic and non-syndromic forms. "The outcome of ADAMTS17 transcriptional suppression on fibrillin-2 assembly was akin to that ascribed to ADAMTSL2, which is mutated in geleophysic dysplasia, another short-stature-brachydactyly condition." (PMID 28176809, 2017).
cleft lip (1 paper, 2025). Congenital defect in the upper lip where the maxillary prominence fails to merge with the merged medial nasal prominences. "However, three SNPs showed some weak evidence of an effect on PRS in the opposite direction to their effect on cleft lip phenotypes: rs62390705 (FBN2, 5q23.3) (P = 0.05), rs126280 (UTP25, 1q32.2) (P = 0.002), and rs4952552 (PKDCC, 2q14.2) (P = 0.04)." (PMID 41075272, 2025).
congenital heart disease (1 paper, 2024). A heart disease that is present at birth. "Furthermore, a few reports have demonstrated that FBN2 in the ascending aorta is overexpressed in congenital heart disease of the bicuspid aortic valve (BAV)." (PMID 38970022, 2024).
congenital muscular dystrophy (1 paper, 2015). A muscular dystrophy that is characterized by diminished muscle tone (hypotonia), progressive muscle weakness and degeneration (atrophy), abnormally fixed joints, spinal rigidity, and delays in reaching motor milestones such as sitting or standing unassisted. "In contrast to heterozygous mutations in Fbn2 causing CCA, with contractures and muscle weakness, results in mice predict that homozygous Fbn2 mutations may cause a form of human congenital muscular dystrophy." (PMID 26114882, 2015). "These new findings demonstrate that loss of fibrillin-2 results in phenotypes similar to those found in congenital muscular dystrophies and that FBN2 should be considered as a candidate gene for recessive congenital muscular dystrophy." (PMID 26114882, 2015). "Fbn2 null mice on the C57Bl/6 background may model this type of congenital muscular dystrophy: death just after birth, contractures, skeletal muscle wasting with adipose tissue replacement, normal lungs, and autosomal recessive inheritance." (PMID 26114882, 2015). "Results indicate that FBN2 is a candidate gene for congenital muscular dystrophy and that strategies aimed at inhibition of abnormal BMP signaling may be applicable to muscular dystrophies." (PMID 26114882, 2015).
corneal stromal dystrophy (1 paper, 2012). "Immunolocalization of fibrillin-2, matrilin-2, matrilin-4, and tenascin-C in normal and stromal dystrophy corneas (maximum and minimum gray levels are 0 and 255, respectively)." (PMID 22876117, 2012). "The present study investigated the expression patterns of fibrillin-2, tenascin-C, matrilin-2, and matrilin-4 in granular and lattice type I corneal stromal dystrophy samples." (PMID 22876117, 2012).
COVID-19 (1 paper, 2022). A disease caused by infection with severe acute respiratory syndrome coronavirus 2. "A total of 6 hub genes were obtained, including: LDHA, TRPA1, PKP2, FBN2, ERO1A, FSCN1, all of which are risk factors for LUAD/COVID-19." (PMID 36157452, 2022).
dolichostenomelia (1 paper, 2018). "Mutations in the FBN2 gene are associated with congenital contractual arachnodactyly (CCA), a condition characterized by dolichostenomelia, pectus deformities, kyphoscoliosis, and congenital contractures." (PMID 30061793, 2018).
Down syndrome (1 paper, 2024). "Additional variants in the connective tissue-related COL11A, PLOD1, and FBN2 genes in disability patients may augment the hypermobility that results from CNS-related hypotonia as reported in a child with Down syndrome." (PMID 38534782, 2024).
exudative retinopathy (1 paper, 2023). "Eyes with intravitreally applied AAV-sh-fbn2 as compared to eyes with injection of AAV-empty vector or developed an exudative retinopathy with involvement of the deep retinal layers, reduction in axial length and reduction in ERG amplitudes." (PMID 37100863, 2023).
granular type I corneal dystrophy (1 paper, 2012). "In conclusion, fibrillin-2 and tenascin-C are largely restricted to developing fetal tissues but become expressed again in granular type I corneal dystrophy and in lattice type I dystrophy." (PMID 22876117, 2012).
Hip dysplasia (1 paper, 2022). The presence of developmental dysplasia of the hip. "In dogs, mutations in FBN2 gene were associated with hip dysplasia." (PMID 36003650, 2022).
homocysteinemia (1 paper, 2024). "A dietary model of homocysteinemia in the chick showed disruption of fibrillin-2 fibers associated with high plasma methionine, and fibrillin-2 deposition has been extensively studied in the Japanese quail (Coturnix japonica)." (PMID 37972149, 2024).